EGFR (epidermal growth factor receptor)
Diseases named in the same sentence as EGFR in open-access papers (continued):
Sharing a sentence is not in itself a finding about the gene and the disease.
lung disease (continued). "Epidermal growth factor receptor (EGFR) is known to regulate airway mucous cell metaplasia (MCM) and mucins expression, but the role of EGFR pathway in the pathogenesis of CF-like lung disease remains unclear." (PMID 40406132, 2025). "While the role of IL-4Rα signaling pathway has been investigated in mouse model of human CF-like lung disease, the role of EGFR signaling pathway in inducing mucins production and other inflammatory outcomes remains unclear." (PMID 40406132, 2025). "The decision-making factors for BSC alone by PS-adjusted multivariate logistic regression analysis were poor ECOG-PS, patients’ desire for BSC, wild type EGFR, presence of the relevant social background, and comorbidities such as dementia, pulmonary disease or psychiatric disorders." (PMID 31882700, 2019). "Thus, this study further characterizes the complex role of EGFR in acute lung injury, which may also translate to EGFR-dependent signaling in other lung diseases." (PMID 36193076, 2022). "Compared with the first platelet count group, the fourth platelet count group contained more women, cardiovascular disease, higher D-dimer, EGFR, lymphocyte, and LDH levels, and less pulmonary disease." (PMID 35775003, 2022). "So far, as already cited above, STAT3, controlled by the EGFR/ADAM17 axis, is a modifier of CF lung disease." (PMID 29540993, 2018). "Epidermal growth factor receptor (EGFR) activation is critical for lung development and the pathology of multiple lung diseases." (PMID 30005089, 2018). "Increased EGFR signaling, TGF-α production, and mucins (MUC5AC and MUC5B) expression have been reported in the airways of CF patients; however, the causative role of EGFR in CF-like lung disease has not been demonstrated, thus warranting further investigation." (PMID 40406132, 2025).
esophageal adenocarcinoma (37 papers, 2007 to 2025). A malignant tumor with glandular differentiation arising predominantly from Barrett mucosa in the lower third of the esophagus. "EGFR was widely expressed in oesophageal adenocarcinoma cell lines and was associated with resistance to 4-hydroxytamoxifen." (PMID 35454796, 2022). "EGFR overexpression is a common feature in oesophageal adenocarcinoma, with higher expression being associated with adverse clinical outcomes and resistance to chemotherapy." (PMID 35454796, 2022). "As regards EGFR mutations, these appear to be rare in gastric and esophageal adenocarcinomas, as also supported by the results in this study wherein all tumours were found to be EGFR wild-type." (PMID 26844548, 2016). "Ferry and other scholars also tested EGFR gene mutations in esophageal adenocarcinoma." (PMID 36701708, 2023). "The EGFR gene (Epidermal Growth Factor Receptor) plays a central role in the progression from Barrett’s esophagus to esophageal adenocarcinoma and has become a focus of increasing interest in molecular studies due to its clinical relevance." (PMID 40149421, 2025). "Studies quantifying EGFR levels in oesophageal adenocarcinoma cell lines in the literature are sparse, but the limited data available are in keeping with this report of higher expression in OE-33 and SK-GT-4 and relatively low expression in OE-19." (PMID 35454796, 2022). "In Barrett’s esophageal adenocarcinoma, leptin appeared to increase cell proliferation and abolish apoptosis via the transactivation of the epidermal growth factor receptor and JNK activation." (PMID 33804101, 2021). "Song and colleagues reported that YAP1 promotes epidermal growth factor receptor (EGFR) expression, conferring chemoresistance in esophageal adenocarcinoma (EAC) cell line." (PMID 30234141, 2018). "As regards esophageal adenocarcinoma, some studies have merely examined the expression of EGFR and HER3, and very few have also reported their prognostic significance." (PMID 26844548, 2016). "In this study we examined the protein expression of EGFR and HER3 as well as the mutational status of EGFR and KRAS in gastric and esophageal adenocarcinoma." (PMID 26844548, 2016). "The aim of this study was to examine the expression and prognostic impact of human epidermal growth factor receptor 1 (HER1/EGFR) and 3 (HER3), as well as the occurrence of EGFR and KRAS mutations in gastric and esophageal adenocarcinoma." (PMID 26844548, 2016). "In the current study, we investigated EGFR in prognosis and chemotherapy resistance esophageal adenocarcinoma patients with a positive response to therapy but who died from tumor recurrence." (PMID 25216514, 2014). "In patients with esophageal adenocarcinoma treated with transhiatal esophagectomy, EGFR expression was related to higher TNM staging and shorter survival." (PMID 22792097, 2012). "EGFR plays an important role in epithelial repair, and patients with GERD have been found to have lower EGFR expression levels than patients with Barrett's esophagus or esophageal adenocarcinoma, indicating that EGFR expression is directly associated with disease progression." (PMID 35646148, 2022).
esophageal adenocarcinoma (continued). "In line with the results from this study, the majority of reports on the prognostic impact of EGFR expression in gastric and esophageal adenocarcinoma have demonstrated correlations with shorter OS, although one study found an independent correlation to a longer OS." (PMID 26844548, 2016). "The aim of this study was to examine the immunohistochemical (IHC) expression of EGFR and HER3, as well as the occurrence of EGFR and KRAS mutations, in gastric and esophageal adenocarcinoma, with particular reference to their relationship with clinicopathological factors, HER2 expression, and OS." (PMID 26844548, 2016). "In addition, EGFR overexpression is involved in CDDP resistance in esophageal adenocarcinoma, and combined treatments with CDDP and EGFR inhibitors show enhanced susceptibility to CDDP-mediated apoptosis in OSCC cells." (PMID 25686830, 2015). "EGFR expression might be assumed as a prognostic marker for esophageal adenocarcinoma." (PMID 22792097, 2012). "However, these trials contained different chemotherapy backbones and as recently reported in oesophageal adenocarcinoma, the monoclonal antibody cetuximab may be less biologically active in this group that anti-EGFR tyrosine kinase inhibitors." (PMID 21811258, 2011). "In 2021, Chen and colleagues reported the use of two heptapeptides (Cy5-labeled QRHKPRE, EGFR-specific, and IRDye800-labeled KSPNPRF, ErbB2-specific) given simultaneously during FME to visualize Barrett’s esophagus (NCT03589443)." (PMID 39513952, 2025). "Immunostaining of 89 esophageal adenocarcinoma samples showed that 58.06% overexpressed c-MET, whereas EGFR overexpression was noted in 27.42%." (PMID 39513952, 2025). "In a recent study, Liang and colleagues analyzed the mRNA expression level of MET and EGFR in esophageal adenocarcinoma by interrogating The Cancer Genome Atlas database, showing that MET mRNA is overexpressed in esophageal adenocarcinoma." (PMID 39513952, 2025). "Efforts to increase diagnostic accuracy through FME have investigated several molecular markers such as EGFR, ErbB2 receptor tyrosine kinase 2, VEGF-A, fluorescent PARP1 inhibitor, chemokine receptor 4, heat shock protein 70, and c-MET for early esophageal adenocarcinoma detection." (PMID 39513952, 2025). "In this in vitro report we demonstrate the applicability of antibody-based NIR-tPDT in esophageal adenocarcinoma (EAC), using the phototoxic compounds cetuximab-IRDye700DX and trastuzumab-IRDye700DX, targeting respectively epidermal growth factor receptor 1 (EGFR) and 2 (HER2)." (PMID 28415738, 2017). "Progress in targeted therapy in esophageal adenocarcinoma has been slow primarily due to failure of conventional markers in other gastrointestinal adenocarcinoma (KRAS, EGFR, PTEN, PIK3CA, and c-MET) to identify patients with esophageal adenocarcinoma who would respond to a targeted therapy." (PMID 28404924, 2017). "A panel of three proteins (EGFR, TRIM44, and SIRT2) had been shown to determine prognosis for esophageal adenocarcinoma (EAC), and a combination of this panel and clinicopathologic features could stratify patients into subgroups with different prognosis." (PMID 25337715, 2014). "This study treated only adenocarcinoma of the oesophagus and GEJ, a subgroup that based on previous studies may be more sensitive to EGFR inhibition." (PMID 21811258, 2011). "However, the role of the EGF/EGFR pathway in the development of gastroesophageal reflux disease (GERD) and its complications (reflux esophagitis (RE), Barrett's esophagus (BE), and esophageal adenocarcinoma (EAC)) remains unclear." (PMID 36092955, 2022).
esophageal adenocarcinoma (continued). "Nevertheless, the TBR of these tracers was less than 1.4 for NDBE and LGD and was less than 1.7 for both heptapeptides in HGD and esophageal adenocarcinoma, suggesting that targeting EGFR and ErbB2 may not provide optimal dysplasia or esophageal adenocarcinoma detection." (PMID 39513952, 2025).
fibrosarcoma (37 papers, 2013 to 2025). A malignant mesenchymal fibroblastic neoplasm affecting the soft tissue and bone. "EGFR‐kinase‐domain duplication (KDD) has been reported in Infantile fibrosarcoma‐like myofibroblastic tumors and cellular mesoblastic nephroma." (PMID 40178433, 2025). "Internal tandem duplications of the whole EGFR kinase domain have been repeatedly reported in some pediatric fusion-negative spindle cell neoplasms morphologically consistent with infantile fibrosarcoma/congenital mesoblastic nephroma." (PMID 39387892, 2024). "These include activating mutations in epidermal growth factor receptor (EGFR) and B-rapidly growing fibrosarcoma (BRAF) or anaplastic lymphoma kinase (ALK) fusions and c-ros oncogene 1(ROS1) receptor tyrosine kinase fusions." (PMID 34572789, 2021). "Recently, preclinical studies combining EGFR blockade with either mTOR or STAT blockade overcame resistance to anti-EGFR monotherapy in EGFR-expressing soft tissue sarcomas and in fibrosarcoma cell line." (PMID 29492209, 2018). "Similarly, EGFR ITDs are described in the setting of infantile fibrosarcoma and congenital mesoblastic nephroma, particularly in classic or mixed subtype, and aids in diagnostics if the tumor is negative for the more commonly identified ETV6::NTRK3 fusion." (PMID 37686670, 2023). "KEAP1-independent regulation of NRF2 includes epidermal growth factor receptor (EGFR)/rat sarcoma virus (RAS)/rapidly accelerated fibrosarcoma (RAF)/extracellular signal-regulated kinase 1/2 (ERK) signaling which activates NRF2 and are also the driver genes of LUAD." (PMID 37305533, 2023). "Both RV and RSV promote activation of the epidermal growth factor receptor (EGFR) and its subsequent signaling involving the rapidly accelerated fibrosarcoma / dual specificity mitogen-activated protein kinase kinase / extracellular signal-regulated kinases (RAF/MEK/ERK) axis." (PMID 31319869, 2019). "In keratinocytes, down-regulation of CD9 was found to increase activity and expression of MMP9 through JNK signaling, while in a fibrosarcoma cell line, epithelial growth factor receptor, EGFR, was an important intermediary for increased release of pro-MMP9 by CD9." (PMID 25889530, 2015). "The potential relationship of CPMT with infantile fibrosarcoma (IF) has been raised by the identification of ETV6::NTRK3 fusion in three cases and, more recently, of a kinase‐domain duplication of EGFR (EGFR‐KDD) in four cases." (PMID 40178433, 2025). "Currently, several biomarker assays are employed for the diagnosis of CRC, specifically focusing on Rat sarcoma virus (RAS) genes, rapidly accelerated fibrosarcoma (RAF) genes, and epidermal growth factor receptor (EGFR) genes." (PMID 39519088, 2024). "Such treatments were considered in 15 of the 23 NSCLC dossiers for the following mutations: anaplastic lymphoma kinase (ALK), rapidly accelerated fibrosarcoma-isoform B (BRAF), epidermal growth factor receptor (EGFR) and the C-ros oncogene 1 (ROS1)." (PMID 32236766, 2020). "Epidermal growth factor receptor (EGFR), vascular endothelial growth factor receptor-2 (VEGFR-2), B rapidly accelerated fibrosarcoma (BRAF), phosphoinositide 3-kinase (PI3k), and mesenchymal–epithelial transition factor (c-Met) are among the protein kinases that are suppressed by quinazolines." (PMID 38398626, 2024). "The group reported that it was not possible to confirm the presence of EGFR in the murine fibrosarcomas by western blot, and therefore the uptake of [O-methyl-11C]gefitinib does not seem to be related to EGFR expression." (PMID 35455447, 2022). "The epidermal growth factor receptor (EGFR), which is upstream of K-Ras and involved in the Ras-rapidly accelerated fibrosarcoma (Raf)-MAP kinase kinase (MEK)-extracellular signal-regulated kinase (ERK) signaling pathway, plays important roles in PDAC development." (PMID 31080558, 2019).
fibrosarcoma (continued). "Similarly IL-1α production and nuclear localization are correlated to ROS levels, EGFR activation and MEK/ERK in fibrosarcoma, skin keratinocytes and in cerebral ischemia injury." (PMID 26919242, 2016). "Studies with Drosophila indicated that during eye development, Spry inhibits signaling downstream of the epidermal growth factor receptor (EGFR) and upstream of rous sarcoma (Ras) but functions at the level of rapidly accelerated fibrosarcoma (Raf) during wing and ovary development." (PMID 24915434, 2014). "The CPMT morphology with EGFR‐KDD in the post‐therapy specimen might be an evolution induced by the treatment, which suggests the hypothesis that CPMT is part of the morphologic spectrum of infantile fibrosarcoma/cellular mesoblastic nephroma." (PMID 40178433, 2025).
metastatic melanoma (37 papers, 2013 to 2025). A melanoma that has spread from its primary site to another anatomic site. "AR expression was positively associated with EGFR in both primary and metastatic melanoma lesions from male as well as female patients." (PMID 37838724, 2023). "In BRAF-mutated metastatic melanoma and EGFR-mutated advanced non-small cell lung cancer (NSCLC), small molecule inhibitors targeting BRAF or EGFR, respectively, significantly increased the overall survival and have become the standard of care in these patients." (PMID 39272879, 2024). "In a cohort of metastatic melanoma patients, we observe an association between LRIG1 and survival in the triple wild-type subtype and in tumors with high EGFR expression." (PMID 33947959, 2021). "On the contrary, PKCδ activity was required in integrin-mediated metastatic melanoma invasion and EGFR-induced migration in fibroblasts." (PMID 27965580, 2016). "Moreover, H2O2-associated EGFR signaling is also vital for tumor metastasis, where murine metastatic melanoma colonies had greater EGFR expression." (PMID 34777681, 2021). "Chromosome 7/EGFR copy number alterations have been studied in primary and metastatic melanoma and speculated to play a role in disease progression." (PMID 26305188, 2015). "This suggests a potential synergistic effect for the use of immunotherapy in combination with EGFR-TKIs, according to the recent evidence of long-lasting antitumor responses of BRAF/MEK inhibitors with immunotherapy in the treatment of BRAF-mutated metastatic melanoma." (PMID 32760402, 2020). "We demonstrate strong enrichment of ecDNA molecules containing EGFR, FGFR2 and MYC from human cancer cells and NRAS ecDNA from human metastatic melanoma with acquired therapeutic resistance." (PMID 36253572, 2022). "Among these pathways, “MAPK signalling”, “signalling by EGFR in cancer”, “PI3K/Akt signalling”, “signalling by SCF-KIT”, “signalling by hedgehog” are the top ranked (amongst top 20; R > 3.5) in both the metastatic melanoma stages." (PMID 26558755, 2015). "In a murine model of metastatic melanoma, IL-2 immunocytokines targeting GD2 and epidermal growth factor receptor (EGFR) suppressed lung and liver metastases, in addition to prolonging survival, when administered after LAK cell reconstitution in immunocompromised mice." (PMID 33803078, 2021). "As a result of our observation that EGFR and MET may regulate the invasion of primary and metastatic melanoma, we decided to put our attention to the invadopodia." (PMID 31638339, 2019).